LDB1 (LIM domain binding 1)
Diseases named in the same sentence as LDB1 in open-access papers (continued):
Sharing a sentence is not in itself a finding about the gene and the disease.
tumor (13 papers, 2003 to 2026). "Microarray and RT-PCRs assays from tumor cDNA confirmed Wnt activation in Ldb1-deficient tumors." (PMID 27713177, 2016). "After splitting the patient samples due to localization, the association between tumor LDB1 expression and Wnt pathway gene expression remained significant for almost all genes analyzed in samples from the proximal colon and for all genes in samples derived from the distal colon." (PMID 27713177, 2016). "In this analysis, association between tumor LDB1 expression and Wnt pathway gene expression remained significant for samples derived from the colon, but not for samples derived from the rectum, again stressing the increased effects of LDB1 in the proximal colon as opposed to the distal colorectum." (PMID 27713177, 2016). "IHC staining of Ki67 in liver and spleen tissues confirmed that the knockdown of Ldb1 has an inhibitory effect on the development of tumor." (PMID 37573405, 2023). "In vivo imaging of small animals showed that fluorescence intake in the Ldb1 knockdown group was lower than that in the control group, suggesting that tumor burden was reduced after Ldb1 knockdown." (PMID 37573405, 2023). "In the mouse model, Ldb1 knockdown significantly inhibited tumor formation and prolonged the survival time." (PMID 37573405, 2023). "According to the sorting of the CCLE database, LDB1 is ubiquitously expressed in more than 20 tumor cell lines, among which AML cell lines have the higher expression." (PMID 37573405, 2023). "Our experiments also showed that LDB1 silence enhanced the anti-tumor activity of oxaliplatin in CRC cells." (PMID 35071313, 2021). "The tumor growth curves showed that silence of LDB1 significantly suppressed the tumor growth of CRC." (PMID 35071313, 2021). "Silence of LDB1 significantly inhibited CRC cell growth in vitro, and CRC cells with low expression of LDB1 had a lower tumorigenesis rate in tumor-bearing nude mice." (PMID 35071313, 2021). "The results of western blot showed that LDB1 was upregulated in tumor tissues of CRC compared with the paracancerous tissues." (PMID 35071313, 2021). "Specifically, 8 out of 12 pairs of tissues (66.7%) showed markedly upregulated LDB1 expression in tumor tissues." (PMID 35071313, 2021). "Surprisingly, however, patients with lower LDB1 expression in the tumor experienced improved overall and metastasis-free survival, thus demonstrating a negative prognostic effect of LDB1 expression in human CRC." (PMID 27713177, 2016). "Tumor Ct values were normalized to the corresponding mucosa and patients were separated into two groups according to a higher or lower expression of LDB1 in comparison with the mucosa." (PMID 27713177, 2016). "As the positive correlation between LDB1 expression and Wnt signaling in tumor samples was at least partly contradictory to previously published data, we aimed to investigate this interaction in detail." (PMID 27713177, 2016). "Greater understanding of the mechanisms by which LMO4, LDB1, and SSBPs regulate tumor cell biology will be important for developing new treatments against this invasive epithelial malignancy." (PMID 27780223, 2016). "To further validate LDB1 as a tumor-promoting factor in CRC, we initiated a series of in vitro experiments using lentiviral vectors to overexpress LDB1 in human CRC cell lines." (PMID 27713177, 2016). "In the present study, patients with LDB1 overexpression in the tumor tissue displayed worse overall survival and metastasis-free survival." (PMID 27713177, 2016). "The in vitro data confirm an influence of LDB1 on the Wnt signaling pathway and tumor cell proliferation." (PMID 27713177, 2016). "The expression of LDB1 was measured via RT-qPCR in 59 clinical tumor and normal mucosa samples and correlated to clinical end-points." (PMID 27713177, 2016).
tumor (continued). "Recently, 12 ETP-ALLs were analyzed by whole genome sequencing and one tumor had an interstitial deletion 5′ of LMO2 and another had a deletion of RLIM which encodes an E3 ubiquitin ligase for the LMO2/LDB1 proteins." (PMID 24465765, 2014). "After the animal study, tumors were excised, taken photos and weighed, and we could clearly see that the tumor size in LDB1-silenced group was significantly smaller than the control." (PMID 35071313, 2021). "More precisely, we aimed to show the role of LDB1 as a tumor suppressor in CRC." (PMID 27713177, 2016). "Finally, inactivation of the LDB1 gene in these cells decreased growth and vascularization of xenografted human tumor cells in vivo." (PMID 27780223, 2016). "It suggests that misexpression of LMO4 and LDB1 expression may play a role in progression of neoplasm." (PMID 12771919, 2003). "In our study, the knockdown of JAK2 and ITGA5, including fibronectin (upstream factors involved in the initial tumor spheroid formation) mediated significant reductions in the levels of LMO2 and LDB1." (PMID 36359204, 2022). "To examine the significance of upstream genes involved in STAT3 activation regulating properties of tumor spheroids, we knocked down FN1, ITGA5, JAK1, JAK2, LDB1, and LMO2 from the cells." (PMID 36359204, 2022). "Our results in this paper confirmed that LDB1 was upregulated in CRC, and its knockdown significantly inhibited CRC cell growth in vitro and suppressed tumor growth in vivo." (PMID 35071313, 2021). "In our present reports, we confirmed that silence of LDB1 significantly inhibited CRC cell growth in vitro, and the animal study also showed that knockdown of LDB1 markedly suppressed the tumor growth of CRC in vivo." (PMID 35071313, 2021). "Moreover, when tumor spheroids cultured on polymer X were transferred to TCP, the levels of STAT3-related proteins, in particular, LMO2 and LDB1, decreased on day 2 of the transfer." (PMID 36359204, 2022). "Moreover, we found that knockdown of LDB1 significantly enhanced the anti-tumor activity of oxaliplatin in CRC cells, and LDB1 knockdown also partly restored the antitumor effect of oxaliplatin in an oxaliplatin-resistant CRC cell line." (PMID 35071313, 2021). "We also evaluate the influence of LDB1 on recurrence-free survival in non-metastatic patients according to tumor localization and again observed a striking effect of LDB1 in the proximal colon; in this cohort (n = 45) no recurrences were observed in patients with low LDB1 expression." (PMID 27713177, 2016).
hematological cancer (1 paper, 2022). "Analysis by LC-MS/MS identified more than 600 Lmo2-interacting molecules in physiological LPs, including the previously reported components of Lmo2 complexes in hematological cancer cell lines, Lyl1, Tal1, Ldb1, Tcf12, Tcf3, and Cbfa2t3 (also known as ETO2 or MTG16)." (PMID 36126774, 2022).
LDB1 also shares sentences with these, for which no sentence is quoted: breast carcinoma (3 papers); head and neck cancer (2); infection (2); anaemia (1); cholestasis (1); glioma (1); Hyperglycemia (1); invasive breast carcinoma (1); lymphoma (1); oropharyngeal tumor (1); retinal detachment (1); retinal disease (1); T-cell acute lymphoblastic leukemia (1).